AHR (aryl hydrocarbon receptor)
Diseases named in the same sentence as AHR in open-access papers (continued):
Sharing a sentence is not in itself a finding about the gene and the disease.
cancer (continued). "Certain cancers can escape immune recognition via AhR signaling pathways." (PMID 29487603, 2018). "Abnormal overexpression and activation of AHR contributed to the development of many cancers." (PMID 30144817, 2018). "Interestingly, the appearance of cancer nodules in the inflamed livers is characterized by a transcriptional upregulation of the two other main regulators of xenobiotic metabolism, namely AHR and CAR." (PMID 29734330, 2018). "Another study showed that overexpression of AHR stimulated the proliferation of cancer cells." (PMID 30144817, 2018). "AHR served as an anti-apoptotic factor in UVB-induced keratinocytes apoptosis.Taken together, these findings indicate that AHR may play an important role in the early events of cancer development." (PMID 30144817, 2018). "Thus, it is critical to have balanced AHR activity for overall homeostasis and prevention of certain pathological conditions that are known to correlate with elevated AHR activity such as cancer." (PMID 30501068, 2018). "Furthermore, the AhR has also been reported to affect cancer stem cells and crosstalk with an ER- and inflammatory factor-associated signaling pathway in the pathologic phase of carcinogenesis." (PMID 29487603, 2018). "In many types of cancer, the existence of AHR agonists has been demonstrated that can augment the expression of inflammatory mediators, MMPs, and transcriptional regulators in a genomic pathway, which leads to downregulation of cell adhesion and upregulation of migration and invasion." (PMID 27752740, 2017). "Role of aryl hydrocarbon receptor in toxicity and cancer is discussed in several documents." (PMID 29511485, 2017). "This suggests that AHR activation may affect the expression of gene networks that could be critical for cancer progression and metastasis." (PMID 29262535, 2017). "AHR is also known to be deeply related to cancer biogenesis." (PMID 28953220, 2017). "Through a combination of biochemical, immunologic and bioinformatic methods, we demonstrate the efficacy of 1MT for cancer immunotherapy may be rationalized in part due to its AHR-activation." (PMID 29190885, 2017). "Taken together, this work lays the foundation for wider implementation of AHR-activating molecules, and the screening parameters that may guide further use of these molecules, to synergize immune-activation with conventional cancer treatment modalities." (PMID 29190885, 2017). "Accumulating in vitro studies also provide substantial support for AHR involvement in cell proliferation, apoptosis, cell migration, immune regulation, and cancer progression." (PMID 27752740, 2017). "Interestingly, HER2, PAX2, AHR, AR, and RUNX factors have each been implicated in cancer stem cell biology (and see “Discussion”)." (PMID 28412963, 2017). "Elevated AhR expression associated with constitutive nonligand activation has been found in several cancers as evidenced by the nuclear localisation of AhR and induced downstream gene Cyp1A1." (PMID 26881027, 2016). "Importantly, no pro-inflammatory genes (with the exception of IL24) and pathways were affected, cancer-related pathways were modulated minimally and only a low AhR-mediated activity was found at sub-cytotoxic concentration of DEP extracts." (PMID 27827897, 2016). "As one of the phytoestrogens due to its polyphenolic structure, kaempferol also exerts anti-proliferative and anti-carcinogenic actions though ER, AR, the aryl hydrocarbon receptor (AhR) and the progesterone receptor (PR) signaling pathways in many types of cancer." (PMID 27231938, 2016). "A recent study on multiple cell lines from the Cancer Cell Line Encyclopedia reported relative high level of AHR mRNA in some cellular models of solid tumor (e.g. pancreatic, liver and chondrosarcoma derived cell lines); low levels were instead detected in many leukemia subtypes." (PMID 26392334, 2015).
cancer (continued). "Such diminished tumorigenicity could be due to a reduction in the number of cancer stem-like cells present in sh-AhR + sh-Aldh1a1 cultures and/or to a less undifferentiated status." (PMID 26242870, 2015). "Given the proven cross-talk between AHR and MAPK pathway and the role of AHR in modulating growth and migration of cancer cells, in the present work we aim to confirm previous associations between the BRAFV600E and AHR overexpression in a large, independent cohort of patients with PTC." (PMID 26392334, 2015). "Thus, our results reveal a role of tryptophan derivatives and the AhR signalling pathway in regulating cancer cell stemness and open a new therapeutic avenue to target stem-like cancer cells." (PMID 26059097, 2015). "We thus tested the hypothesis that constitutive AHR signaling may drive IL-6 production also in other human cancer cells." (PMID 24657910, 2014). "In addition, in vitro cleavage assay in cancer cells is response to AhR cleavage fragment in a dose-dependent manner." (PMID 25226618, 2014). "Several reports reveal constitutive AhR signaling within various cancer types." (PMID 24755659, 2014). "Moreover, an autocrine signaling loop involving IL-6, STAT3, and AhR was found to sustain the constitutive expression of IDO1 in human cancer cells." (PMID 25360135, 2014). "As angiogenesis has a critical role in the metastatic process, which is the primary cause of mortality in cancer patients, the down-regulation of chemokine (C-C motif) ligand 2 (CCL2) and vascular endothelial growth factor A (VEGFA), subsequent to AhR knockdown was deemed of high significance." (PMID 24932473, 2014). "The formation of the E-cadherin/AhR/Skp2 complex and ubiquitination of E-cadherin induced by kynurenine is also detectable in A549 cells, indicating a general mechanism of kynurenine-induced proteolysis of E-cadherin in different cancer cells." (PMID 25060643, 2014). "Additionally, PAH-induced AhR activation was shown to play a role in cancer promotion and progression." (PMID 24932473, 2014). "In addition, knockdown AhR activity also dramatically reduced peritoneal dissemination, which helps uncover mysteries function of cancer cells and repertory." (PMID 25226618, 2014). "Pharmaceutical manipulation of AHR activity could prove to be one prong of a multi-pronged, personalized treatment plan for such cancers." (PMID 25286307, 2014). "Previous reports have revealed that phthalates promote cancer cell migration, invasion and epithelial-mesenchymal transition, which may explain the cancer progression observed in both ER-dependent and AhR-dependent pathways." (PMID 25081364, 2014). "Transfection cancer cells with siRNA-Calpain-10, but not scramble siRNA (data not shown), caused reversion of AhR down-regulation." (PMID 25226618, 2014). "We thus hypothesized that IDO may activate its own expression in human cancer cells via an autocrine AHR–IL-6-STAT3 signaling loop." (PMID 24657910, 2014). "Considering that exposure to pesticides may lead to various human diseases, including cancer, the implication of AhR in this process should be carefully assessed." (PMID 25257533, 2014). "Certain cancers have developed the ability to evade their own clearance through use of the AHR." (PMID 25324842, 2014). "The aryl hydrocarbon receptor (AHR) is a ligand-activated transcription factor that plays roles in tumorigenesis, is regulated by exogenous lipophilic chemicals, and has been explored as a therapeutic target for cancer therapy." (PMID 24171117, 2013). "We expected that AhR was related to the process of cancer cell malignancy." (PMID 24330582, 2013). "As challenges to targeted therapies include acquired and primary resistance, targeting AhR could be a possible way to circumvent the emergence of targeted therapy resistance and cancer recurrence." (PMID 25068070, 2013). "Ligand-activated AHR inhibits the growth of some human cancers cell lines." (PMID 24171117, 2013).
cancer (continued). "Matrix metalloproteinases (MMP) are key players in cancer invasion and metastasis and provide a possible mechanism by which AhR may modulate the invasive potential of cancer cells." (PMID 25068070, 2013). "In addition, we evaluated the expression of AhR across 967 cancer cell lines using the recently developed cancer cell line encyclopedia." (PMID 22815870, 2012). "Furthermore, analysis of expression data from 967 cancer cell lines revealed that AhR is expressed in multiple different cancer types supporting the intriguing possibility of targeting the AhR for therapy in a number of cancers." (PMID 22815870, 2012). "The AhR's ability to regulate cell proliferation may also be exploited for therapeutic purposes including cancer treatment." (PMID 20957046, 2010). "The molecular targets of tranilast in cancer have been unknown, but here we demonstrate it is an aryl hydrocarbon receptor (AHR) agonist and this plays a key role." (PMID 21072210, 2010). "Together these observations suggest that AhR activation may be a cancer counteracting mechanism in the prostate." (PMID 20140206, 2010). "Evidently, further studies are required to delineate the role of the AHR in cancer, and whether different agonists will have similar effects or not." (PMID 21072210, 2010). "Its action on cancer may be partially due to an activation of the AhR pathway and the interaction of the AhR with the ER." (PMID 22254019, 2010). "Certain flavonoids are capable of inducing CYP1A1 activity via the AhR in cancer cell line models." (PMID 19531241, 2009). "In particular, planar congeners of dioxins and dioxin-like compounds like 2,3,7,8-TCDD show high toxicity by binding to the aryl hydrocarbon receptor (AhR), causing cancer and various non-cancer effects including immunotoxicity, neurological effects, and cardiovascular disease." (PMID 41501044, 2026). "By stratifying patients based on their AHR status, we aimed to uncover personalized immunomodulatory strategies that could potentiate immune responsiveness in this otherwise immunologically refractory cancer type." (PMID 41357201, 2025). "Thus, DIM induced cancer cell ferroptosis through the AHR/NRF2/GPX4 axis." (PMID 40765830, 2025). "Together, these findings identify a host–microbe metabolic axis in which microbial I3A suppresses cancer cell ferroptosis through aryl hydrocarbon receptor–c-Jun N-terminal kinase signaling, which may have critical implications for redox-based cancer therapies." (PMID 41354345, 2025). "However, a study showed that hypomethylation may repress the population fighter genes, the aryl hydrocarbon receptor (AHR), in turn leading to the accumulation of environmental pollutants and subsequently increasing the risk of cancers among smokers." (PMID 40003580, 2025). "A common view of Trp-Kyn metabolism in cancer immunomodulation is that it promotes immune suppression through two main mechanisms: metabolic competition, where Trp depletion leads to T cell starvation, and the accumulation of Kyn, which acts as a ligand for the aryl hydrocarbon receptor (AhR)." (PMID 40554511, 2025). "These metabolites act primarily through the aryl hydrocarbon receptor (AhR) and the PXR, and in GI cancers they may exert protective effects—for example, IAA and IPA can strengthen the epithelial barrier and suppress inflammation, thereby reducing cancer risk." (PMID 41357193, 2025). "Both AhR agonists and antagonists may have potential cancer-preventive activity." (PMID 38518996, 2024). "Thus, the epigenetic modification of the AhR itself or its involvement in the epigenetic mechanism may contribute to cancer development." (PMID 39339278, 2024). "Consequently, CYP1A1 expression detected in the cancer cells of some NSCLC samples was probably controlled by other transcriptional regulatory pathways that were not linked to activation of AhR signaling." (PMID 39199657, 2024).
cancer (continued). "Basically, AHR functions as a ligand-activated transcription factor integral to cellular homeostasis, governing various physiological and pathological processes, including xenobiotic detoxification, metabolism, cardiovascular regulation, immunomodulation, and cancer development." (PMID 38612627, 2024). "Therefore, AhR expression/activation may impact the migration, proliferation, and survival of cancer cells." (PMID 39339278, 2024). "AhR functions as a regulator of cell fate decisions to promote the polarization of resident memory T cells as well as inhibit T central memory cell differentiation, suggesting that AhR signaling pathway activation may have therapeutic implications in cancer immunotherapy." (PMID 39031507, 2024). "Additionally, since AhR translocates from the cytosol to the nucleus upon activation, the comparison of the nuclear and cytosolic expression of AhR may provide valuable insights into the differential roles of AhR in each cancer type." (PMID 38680496, 2024). "Dietary omega-3 fatty acids may play role in inhibiting AhR-dependent cancer progression." (PMID 38612589, 2024). "Additionally, we describe the important role of AhR in the regulation of cancer cell metabolism and relevant pathways, which may be used to better understand the potential of anticancer therapies." (PMID 38434684, 2024). "However, the role of the AhR pathway in microbiome-mediated cancer remains unlocked." (PMID 38448800, 2024). "Therefore, AhR modulation has been suggested as a cancer chemoprevention strategy, since the pathways controlled by this transcription factor are critical in the beginning and during the development of cancer." (PMID 39339278, 2024). "In addition, the cancer patient survival data showed that a high level of AhR in cancers of the lung, breast, esophagus, kidney, and uterus predicts better overall survival of the patients, whereas the survival probability of lower AhR-expressing cancers is significantly poorer." (PMID 38518996, 2024). "Notably, the AhR-driven modulation of EGFR function has been investigated in various cancers." (PMID 39211042, 2024). "However, direct overexpression of AhR showed different regulating roles in different cancers." (PMID 38434684, 2024). "However, it is unknown whether the cancer chemopreventive effects of omeprazole is dependent on AhR activation." (PMID 38518996, 2024). "Furthermore, through signaling pathways involving protein kinase A (PKA), nuclear factor κB (NF-kB), and steroid receptor-coactivator-1 (Src1) in the cytosol, AhR might influence aspects such as cancer cell survival and resistance." (PMID 38680496, 2024). "Therefore, AhR is believed to have a dual function in cancer." (PMID 38792249, 2024). "The KYN/AhR axis may facilitate cancer cells’ survival, migration, and chemoresistance." (PMID 37373581, 2023). "Also, only two cell lines were used, which had some different responses to AHR and ELAVL1 modulation; so, further investigation into the mechanisms causing such differences and the stratification of cancer subtypes that would benefit most from such modifications are required." (PMID 37685961, 2023). "Furthermore, the aryl hydrocarbon receptor (AHR) plays a crucial role in PAHs metabolism by regulating the expression of genes involved in the initiation, promotion, and progression of various types of cancer." (PMID 37542205, 2023). "Therefore, AhR knockdown promotes ferroptosis of Erastin-induced cancer cells." (PMID 37056388, 2023). "However, considering its critical roles in barrier biology, AHR inhibition may be carefully applied for cancer therapy, although branches of Trp catabolism converge on AHR activity in a majority of tumors." (PMID 37394584, 2023).
cancer (continued). "Consequently, the AhR may play a critical role in the TME of various cancer types by modulating the recruitment and function of infiltrating immune cells." (PMID 37696458, 2023). "Similarly, the role of AhR-mediated functions in cancer development is not limited to the generation of carcinogenic metabolites, but also feeds into various other cancer-related processes, including cell migration, cell transformation, inflammation, and epigenetic processes." (PMID 37492623, 2023). "Since AHR is often overexpressed in cancer, it is frequently targeted in the hope of increasing the effectiveness of cancer treatment in various malignancies, and in this case, it could be targeted in the hopes of increasing gemcitabine efficiency in PC treatment." (PMID 37685961, 2023). "AHR may play a role in modulating the immune response against cancer." (PMID 37760608, 2023). "However, the exact mechanism of the AhR involvement with the quercetin anti-cancer action is still unknown." (PMID 36982245, 2023). "However, the impact of the AhR could be cancer stage-dependent, and other evidence suggests that AhR is overexpressed in cancer colon tissue in comparison with healthy tissue." (PMID 36077780, 2022). "In addition, KYN, KYNA, and XA are all inducers of AHR activity, which could drive AHR activity and promote cancer cell migration." (PMID 35296014, 2022). "Therefore, the antitumor activity of AhR agonist or antagonist remains to be clarified in clinical setting and whether these drugs act directly on cancer cells or by modulating antitumor immunity, thus suggesting synergistic effect when combined with ICI." (PMID 35173722, 2022). "The tryptamine receptor TAAR1 is a potential cancer prognosis biomarker and it could induce the transcription of the aryl hydrocarbon receptor (AHR) target gene cytochrome P450 1A1 (CYP1A1), leading to the activation of the conversion of organic compounds to cytotoxic or carcinogenic species." (PMID 36232383, 2022). "Consequently, such deregulation of AHR activity has important implications in cancer." (PMID 35465323, 2022). "A variety of molecular signaling pathways have been previously linked to AHR-mediated tumorigenesis whether or not in a cancer type-specific background and/or driven by AHR agonists." (PMID 35710704, 2022). "Thus, understanding how the ligand selectivity of AHR contributes to these pro- and anti-tumorigenic functions might provide information on AHR as a novel therapeutic target for cancer." (PMID 36292946, 2022). "As already mentioned, these noxious effects are claimed to be ascribed to the interaction of TCDD to the AhR, protein which translocates into the nucleus to promote the transcription of several factors involved in survival, invasive and migrative potential of cancer cells." (PMID 35163492, 2022). "However, few studies have actually focused on the immunotherapeutic value of AhR in human cancers." (PMID 34290693, 2021). "Consequently, the IDO-Kyn-AhR signaling pathway provides a new target in cancer immunotherapy as discussed recently and AhRR may provide an important tool to inhibit this pathway." (PMID 33763068, 2021). "Finally, the stimulation of AhR leads to activation of MAPK signaling which may be involved in cancer cell proliferation." (PMID 33499346, 2021). "Moreover, previous studies revealed that KYN may promote cancer cell survival and motility by interaction with AhR." (PMID 34299117, 2021). "Importantly, the proteins encoded by HSP90AA1 and HSP90AB1 genes act in several pivotal roles in the cancer development through other relevant signaling pathways identified in this study, such as the ones involving the aryl hydrocarbon receptor (AhR), glucocorticoid receptor and nitric oxide (NO)." (PMID 33656060, 2021). "Interestingly, however, AhR expression had some prognostic value in some cancers, especially PAAD." (PMID 34290693, 2021).